LARP7 (La ribonucleoprotein 7, transcriptional regulator)
Description:
RNA-binding protein that specifically binds distinct small nuclear RNA (snRNAs) and regulates their processing and function. Specifically binds the 7SK snRNA (7SK RNA) and acts as a core component of the 7SK ribonucleoprotein (RNP) complex, thereby acting as a negative regulator of transcription elongation by RNA polymerase II. The 7SK RNP complex sequesters the positive transcription elongation factor b (P-TEFb) in a large inactive 7SK RNP complex preventing RNA polymerase II phosphorylation and subsequent transcriptional elongation. The 7SK RNP complex also promotes snRNA gene transcription by RNA polymerase II via interaction with the little elongation complex (LEC). LARP7 specifically binds to the highly conserved 3'-terminal U-rich stretch of 7SK RNA; on stimulation, remains associated with 7SK RNA, whereas P-TEFb is released from the complex. LARP7 also acts as a regulator of mRNA splicing fidelity by promoting U6 snRNA processing. Specifically binds U6 snRNAs and associates with a subset of box C/D RNP complexes: promotes U6 snRNA 2'-O-methylation by facilitating U6 snRNA loading into box C/D RNP complexes. U6 snRNA 2'-O-methylation is required for mRNA splicing fidelity. Binds U6 snRNAs with a 5'-CAGGG-3' sequence motif. U6 snRNA processing is required for spermatogenesis (By similarity).
Synonyms: hLARP7; PIP7S; HDCMA18P; DKFZP564K112; ALAZS
Tractability: Small molecule: a structure with a bound ligand is known. PROTAC: UniProt records ubiquitination sites on it; ubiquitination databases record sites on it; its protein half-life has been measured; a small molecule that binds it is known.
Gene: Protein-coding gene on chromosome 4 (112,636,990 to 112,657,858, forward strand). Ensembl gene ENSG00000174720.
Subcellular location: Nucleus, nucleoplasm
Subcellular location (Human Protein Atlas): Cytosol; Nucleoplasm
Gene Ontology:
Molecular function: 7SK snRNA binding; protein binding; RNA binding; U6 snRNA binding; nucleic acid binding
Biological process: box C/D sno(s)RNA 3'-end processing; negative regulation of transcription by RNA polymerase II; negative regulation of viral transcription; positive regulation of protein localization to Cajal body; positive regulation of snRNA transcription by RNA polymerase II; regulation of mRNA splicing, via spliceosome; U6 2'-O-snRNA methylation; negative regulation of transcription elongation by RNA polymerase II; spermatogenesis; RNA processing
Cellular component: 7SK snRNP; nucleoplasm; nucleus; ribonucleoprotein complex
Genetic constraint (gnomAD): Loss-of-function variants: 36 observed, 42.1 expected, observed/expected ratio (o/e) 0.86, 90% interval 0.65 to 1.13. The synonymous counts are far from expectation, so gnomAD's model fits this gene poorly and the ratio says little. Missense variants: 564 observed, 503.24 expected, observed/expected ratio (o/e) 1.12, 90% interval 1.04 to 1.2. Synonymous variants: 200 observed, 157.1 expected, observed/expected ratio (o/e) 1.27, 90% interval 1.13 to 1.43.
Homologues: Orthologues: chimpanzee LARP7 (99% identical), macaque LARP7 (98% identical), dog LARP7 (89% identical), rabbit LARP7 (87% identical), pig LARP7 (87% identical), guinea pig LARP7 (81% identical), mouse Larp7 (80% identical), rat Larp7 (80% identical), tropical clawed frog larp7 (61% identical), zebrafish larp7 (52% identical), mouse Larp7-ps (33% identical), Drosophila melanogaster Larp7 (26% identical). Paralogues in human: SSB (17% identical), LARP6 (16% identical), LARP4 (14% identical), LARP4B (13% identical), LARP1B (12% identical), LARP1 (12% identical).
Diseases named in the same sentence as LARP7 in open-access papers:
LARP7 is named in the same sentence as 40 diseases in open-access papers, as found by Europe PMC text mining. Sharing a sentence is not in itself a finding about the gene and the disease. The quoted sentences say what the papers report.
Alazami syndrome (11 papers, 2016 to 2026). "Paradoxically, instead of exerting overgrowth effects, biallelic inactivation of LARP7 is linked to Alazami syndrome, a human neurodevelopmental disorder characterized by growth restriction and cognitive impairment." (PMID 41872527, 2026). "There have been 24 different LARP7 variants associated with Alazami syndrome including frameshift (n = 17), splicing (n = 5), and large deletion (n = 2)." (PMID 40548259, 2025). "We report three new individuals with Alazami syndrome and functional characterization of LARP7 variants in this study." (PMID 40548259, 2025). "Inactivating mutations of LARP7 have been linked to Alazami syndrome, a human NDD characterized by severe intellectual disability." (PMID 39479517, 2024). "In humans, inactivating mutations of LARP7 have been linked to Alazami syndrome, a human NDD with other comorbidities." (PMID 39479517, 2024). "Currently, 24 patients from 12 families are described as having Alazami syndrome and recessive variants in LARP7." (PMID 32244554, 2020). "Biallelic LARP7 loss-of-function variants underlie Alazami syndrome characterized by growth retardation and intellectual disability." (PMID 31467394, 2019). "The LARP7-associated phenotype, named Alazami syndrome, has been broadened by the description of a total of 18 individuals with biallelic LARP7 mutations." (PMID 31467394, 2019). "In this study, we hypothesized that two affected siblings with the LARP7 variant of uncertain significance (VUS) had a phenotypic match of Alazami syndrome." (PMID 40548259, 2025). "We report the first missense LARP7 variant to be causative of Alazami syndrome." (PMID 40548259, 2025). "The human La and Larp7 proteins have also been implicated in telomere maintenance:29,30 Larp7 loss-of-function mutations in patients with Alazami syndrome being associated with very short telomeres and Larp7 knockdown causing a reduction in telomerase activity in cancer cells." (PMID 35217638, 2022). "Alazami syndrome is usually caused by frameshift variants in LARP7." (PMID 32244554, 2020). "Here, we report a boy with severe NDD, absent speech with profound neurosensorial deafness, growth restriction, and facial dysmorphisms, resulting from double homozygosity in LARP7, causing Alazami syndrome and OTOG, associated with a very rare form of autosomal recessive neurosensorial deafness." (PMID 32244554, 2020). "To date, the clinical effect of deleterious variants in LARP7 is restricted to Alazami syndrome." (PMID 32244554, 2020). "Because both wild-type and individuals heterozygous for a loss-of-function mutation in LARP7 display short telomeres and progressively shorter initial telomere length, it is reasonable to assume the developmental symptoms of Alazami syndrome are distinct from the telomeric symptoms." (PMID 27766953, 2016). "Because human LARP7 is the most likely ortholog of the Tetrahymena p65 protein, which is required for telomerase activity in that organism, we investigated the effects of LARP7 silencing in human cells as well as in two distinct families with Alazami syndrome (loss of function of LARP7)." (PMID 27766953, 2016). "Alazami syndrome is fully penetrant, and LARP7 is expressed throughout the whole body with the highest expression in the brain." (PMID 40548259, 2025). "In our study, we performed a qPCR gene expression experiment and measured the relative expression levels of LARP7 in three individuals with Alazami syndrome compared to WT control." (PMID 40548259, 2025). "Building upon these findings, we use Emx1-Cre and nestin-Cre to knock out Larp7, a gene linked to a human NDD called Alazami syndrome (OMIM, # 615071)." (PMID 39479517, 2024). "LARP7, an interacting protein of CLCN3 at the protein level, has been reported as a causative of Alazami syndrome characterized by failure to thrive, short stature, and DD symptoms." (PMID 38025430, 2023). "We reviewed the medical literature for Alazami syndrome and LARP7." (PMID 40548259, 2025).
Alazami syndrome (continued). "Furthermore, we use Emx1-Cre and nestin-Cre to knock out Larp7, a gene linked to a human NDD called Alazami syndrome." (PMID 39479517, 2024). "Alazami syndrome (MIM 615071) is an ultra-rare autosomal recessive syndromal form of NDD, described for the first time in 2012 in an inbred Saudi Arabian family with a novel form of primordial dwarfism, due to a homozygous variant in LARP7 (OMIM 612026) gene." (PMID 32244554, 2020). "We first determined the effects of LARP7 knockdown on telomere length, telomerase (hTERT) splicing and enzymatic activity in human cell culture models, and then assessed the telomere biology of both affected and unaffected relatives of Alazami syndrome patients." (PMID 27766953, 2016).
breast carcinoma (7 papers, 2014 to 2024). "LARP7 is expressed at low levels in breast cancer; therefore, elevated levels of this protein are associated with overall improvement and longer recurrence-free survival." (PMID 36052258, 2022). "The association between cancer progression and reduced LARP7 expression was also confirmed in a panel of breast cancer cell lines." (PMID 25053741, 2014). "LARP7 functions as a tumor suppressor gene in gastric cancer and can suppress P-TEFb activity to inhibit breast cancer progression and metastasis." (PMID 34512654, 2021). "To test this, we stably knocked down LARP7 in two noninvasive breast cancer cell lines T47D and BT474." (PMID 25053741, 2014). "Taken together, these data indicate that silencing LARP7 in noninvasive breast cancer cells shifts the P-TEFb equilibrium from the inhibitory 7SK snRNP to the active SEC, leading to increased P-TEFb activity and expression of EMT-related transcription factors." (PMID 25053741, 2014). "As downregulation of HEXIM1 in human breast cancer has been reported previously, we focused on LARP7 in this study." (PMID 25053741, 2014). "In two independent clinical data sets containing LARP7 information, LARP7 expression was markedly reduced in breast cancer tissues, especially in the invasive carcinoma, when compared with the matched normal tissues." (PMID 25053741, 2014). "The role of the LARP family proteins in human cancer is so far poorly known, and our study is the first demonstration that LARP7 functions as a potential suppressor of human breast cancer metastasis." (PMID 25053741, 2014). "Taken together, these data suggest a model that LARP7 is downregulated in invasive human breast cancer cells, leading to a decrease in 7SK snRNA and subsequently 7SK snRNP." (PMID 25053741, 2014). "To determine the precise role of LARP7 in breast cancer development, we first knocked down the expression of LARP7 in the untransformed MCF10A cells using short hairpin RNAs (shRNAs)." (PMID 25053741, 2014). "Taken together, our results suggest that knockdown of LARP7 enhances breast cancer EMT and CSC expansion in vitro and metastasis in vivo." (PMID 25053741, 2014). "Taken together, these data indicate that LARP7 likely suppresses the survival and progression of malignant breast cancer cells through 7SK snRNP-dependent inhibition of P-TEFb." (PMID 25053741, 2014). "Taken together, our study has demonstrated that LARP7 functions as a potential tumor suppressor in human breast cancer by suppressing the activity of P-TEFb and inhibiting EMT, invasion, and metastasis." (PMID 25053741, 2014). "Here, we show that in noninvasive human breast cancer cells, disruption of this complex by knocking down LARP7 releases P-TEFb, redistributing it to the transcriptionally active SEC complex." (PMID 25053741, 2014). "LARP7 is a potential tumor suppressor in gastric and breast cancer." (PMID 38791307, 2024). "We next examined LARP7 protein levels by immunohistochemistry in a human breast cancer tissue array containing 150 duplicated samples of normal human breast tissue, benign tumors, ductal carcinoma in situ (DCIS), and invasive ductal carcinoma of varying pathological grades." (PMID 25053741, 2014). "Interestingly, the LARP7-overexpressing cells formed significantly fewer colonies than those harboring the control vector, suggest that re-expression of LARP7 impairs survival of these metastatic breast cancer cells." (PMID 25053741, 2014). "Thus, downregulation of LARP7 correlates with breast cancer progression, metastasis, and poor prognosis." (PMID 25053741, 2014). "Next, to investigate whether re-introducing LARP7 in metastatic breast cancer cells could block or reverse the malignant phenotypes, we transfected MDA-MB-231 cells with cDNAs encoding either WT LARP7 or the LARP7 Δ2A mutant." (PMID 25053741, 2014).
breast carcinoma (continued). "We further analyzed the NKI295 breast cancer microarray data set that contains information on the clinical outcomes of patients to investigate the correlation between LARP7 level and clinical characteristics." (PMID 25053741, 2014). "Thus, the sequestration of P-TEFb by 7SK snRNP is an effective anti-cancer mechanism, and the key 7SK snRNP component LARP7 is a potential tumor suppressor that specifically blocks breast cancer progression and metastasis." (PMID 25053741, 2014). "Less LARP7 protein is made in breast cancer cells compared to healthy cells." (PMID 25053741, 2014). "Decreased levels of LARP7 and 7SK snRNA redistribute P-TEFb to the transcriptionally active super elongation complex, resulting in accelerated transcription of transcription factors that promote breast cancer epithelial-mesenchymal transition, invasion, and metastasis." (PMID 32070401, 2020). "Finally, to determine whether LARP7 KD also results in an increase in breast cancer metastasis in vivo, the T47D control or shLARP7-2 cells were injected intravenously into the nude mice, and lung metastasis was examined 12 weeks later." (PMID 25053741, 2014). "By knocking down LARP7, we released P-TEFb from the 7SK snRNP and stimulated the P-TEFb-dependent transcription of EMT-related genes, resulting in breast cancer EMT and enhanced invasion and metastasis." (PMID 25053741, 2014). "Of the known components in the three major P-TEFb-containing complexes, the 7SK snRNP, the Brd4-bound complex, and the SEC, only LARP7 and HEXIM1, two signature components of the 7SK snRNP, showed consistent alteration in human breast cancer tissues." (PMID 25053741, 2014). "If the increased P-TEFb activity upon LARP7 KD is responsible for the EMT and enhanced transformation of breast cancer cells, inhibition of P-TEFb is expected to reverse the process." (PMID 25053741, 2014). "Because P-TEFb is a transcription elongation factor that most likely affects breast cancer progression at the level of transcription, we decided to examine the expression of a panel of EMT regulators in the two T47D LARP7 KD cell lines (shLARP7-1 and shLARP7-2)." (PMID 25053741, 2014). "We found that the Brd4-P-TEFb complex was also increased moderately upon LARP7 KD (data not shown), suggesting the possibility that Brd4 may also play a role in facilitating the P-TEFb-dependent breast cancer progression." (PMID 25053741, 2014).
gastric cancer (4 papers, 2014 to 2021). A primary or metastatic malignant neoplasm involving the stomach. "Microsatellite-instability induced frame-shift mutations resulting in truncations to the RRM2 region of LARP7 (required for its interaction with 7SK RNA) have been detected in a significant proportion of gastric cancer cases." (PMID 26501340, 2015). "Finally, frequent frameshift mutations in the LARP7 gene are found in gastric cancers, pointing to a tumor suppression function for LARP7." (PMID 34146121, 2021). "Moreover, microsatellite instability (MSI)-induced frameshift mutations in the LARP7 gene have been detected in a significant population of gastric cancer samples, implicating a potential tumor suppressor role of LARP7 in cancers." (PMID 25053741, 2014). "The Δ2A mutant was originally found in microsatellite instable gastric cancer and contains a deletion of two adenosines from a microsatellite repeat of 8 A's (nucleotides 1206–1213) in the LARP7 C-terminal region, leading to a frameshift deletion of the C-terminal region of LARP7." (PMID 25053741, 2014).
Intellectual disability (4 papers, 2014 to 2025). "Finally, an inactivating mutation of LARP7 has been linked to a novel form of familial Primordial Dwarfism characterized by facial dysmorphism and intellectual disability." (PMID 25053741, 2014). "Moreover, the phenotype in subjects with biallelic LARP7 variants is more severe than that in our patient as affected individuals show a spectrum of growth retardation ranging from short stature to primordial dwarfism associated with severe intellectual disability and distinct facial features." (PMID 31467394, 2019).
heart failure (3 papers, 2023 to 2024). Inability of the heart to pump blood at an adequate rate to meet tissue metabolic requirements. "For example, cardiomyocyte‐specific expression of Larp7 protects against heart failure by activating Sirt1‐Pgc1a‐mitochondrial pathway." (PMID 38818612, 2024).
atherosclerosis (2 papers, 2024 to 2025). A disease characterized by the build-up of fatty material and calcium deposition in the arterial wall resulting in partial or complete occlusion of the arterial lumen. "In our previous study, we discovered that suppressing Larp7 accelerates senescence by inhibiting Sirt1 activity, resulting in increased atherosclerosis in high‐fat diet (HFD) fed and ApoE deficient (ApoEKO) mice." (PMID 38818612, 2024). "Our previous studies have established Larp7 as a new activator of Sirt1, and the reduced Sirt1 activity has been implicated in atherosclerosis." (PMID 38818612, 2024). "The La Ribonucleoprotein Domain Family Member 7 (Larp7), a protein that promotes senescence by decreasing SIRT1 function, led to the development of atherosclerosis in ApoE-deficient mice when subjected to a high-fat diet." (PMID 41567643, 2025). "To demonstrate the protective role of Larp7 overexpression in atherosclerosis, we performed Oil red O staining to examine lipid‐laden plaques in atherosclerotic lesions." (PMID 38818612, 2024). "In summary, our study provides evidence that Larp7 overexpression holds promise as an approach to inhibit cellular senescence and prevent atherosclerosis." (PMID 38818612, 2024). "Here, to explore the therapeutic potential of Larp7 overexpression in treating atherosclerosis, we induced Larp7 overexpression in a ApoE knockout (ApoEKO) mouse by utilizing Tet‐on system and Cre‐loxp system." (PMID 38818612, 2024). "LARP7 depletion or suppression of Larp7‐Sirt 1 axis exacerbated cellular senescence and atherosclerosis." (PMID 38818612, 2024). "In sum, our study directly proved Larp7 overexpression activates Sirt1 and suppresses cellular senescence pathway, thereby exhibiting a therapeutic role in atherosclerosis." (PMID 38818612, 2024). "To explore the therapeutic potential of Larp7 overexpression in treating atherosclerosis, we first generated a tetO‐controlled and Cre‐activated Larp7 gain‐of‐function mouse (named as Larp7tetO) by using CIRSPR‐Cas9‐mediated homology recombination (HR)." (PMID 38818612, 2024). "And Larp7 restoration in this study inhibited atherosclerosis development." (PMID 38818612, 2024). "However, it is still unclear whether overexpressing Larp7 could be a targeted approach for treating atherosclerosis." (PMID 38818612, 2024). "But we did not provide a direct proof for the protective role of Larp7 overexpression, which is important to explore a new approach for anti‐atherosclerosis therapy." (PMID 38818612, 2024). "However, there has been no direct evidence demonstrating Larp7 per se could attenuate atherosclerosis." (PMID 38818612, 2024).